MIR7-1 (microRNA 7-1)
Synonyms: hsa-mir-7-1; MIRN7-1; mir-7-1
Gene: MicroRNA gene on chromosome 9 (83,969,748 to 83,969,857, reverse strand). Ensembl gene ENSG00000284179.
Gene Ontology:
Biological process: miRNA-mediated post-transcriptional gene silencing
Cellular component: RISC complex
Homologues: Orthologues: chimpanzee ptr-mir-7-1 (100% identical), rabbit MIR7-1 (100% identical), macaque mml-mir-7-1 (99% identical), guinea pig MIR7-1 (95% identical), mouse Mir7-1 (95% identical), dog MIR7-1 (93% identical), pig ssc-mir-7-2 (93% identical), rat Mir7-1 (82% identical), tropical clawed frog xtr-mir-7-1 (82% identical), zebrafish dre-mir-7ba (70% identical), Drosophila melanogaster mir-7 (50% identical). Paralogues in human: MIR7-3 (65% identical).
Diseases named in the same sentence as MIR7-1 in open-access papers:
MIR7-1 is named in the same sentence as 2 diseases in open-access papers, as found by Europe PMC text mining. Sharing a sentence is not in itself a finding about the gene and the disease. The quoted sentences say what the papers report.
breast carcinoma (1 paper, 2015). "The transcription factor Forkhead box P3 (FOXP3) which also positively regulates miR-7 expression in breast cancer has been found to have potential binding regions in the locality of MIR7-1 and MIR7-2 genes." (PMID 26308064, 2015).
MIR7-1 also shares sentences with these, for which no sentence is quoted: hepatocellular carcinoma (1 paper).